NOCT (nocturnin)
Description:
Phosphatase which catalyzes the conversion of NADP(+) to NAD(+) and of NADPH to NADH. Shows a small preference for NADPH over NADP(+). Represses translation and promotes degradation of target mRNA molecules. Plays an important role in post-transcriptional regulation of metabolic genes under circadian control (By similarity). Exerts a rhythmic post-transcriptional control of genes necessary for metabolic functions including nutrient absorption, glucose/insulin sensitivity, lipid metabolism, adipogenesis, inflammation and osteogenesis (By similarity). Plays an important role in favoring adipogenesis over osteoblastogenesis and acts as a key regulator of the adipogenesis/osteogenesis balance (By similarity). Promotes adipogenesis by facilitating PPARG nuclear translocation which activates its transcriptional activity (By similarity). Regulates circadian expression of NOS2 in the liver and negatively regulates the circadian expression of IGF1 in the bone (By similarity). Critical for proper development of early embryos (By similarity).
Synonyms: CCRN4L; NOC; CCR4L; Ccr4c
Tractability: Small molecule: a structure with a bound ligand is known. PROTAC: ubiquitination databases record sites on it; its protein half-life has been measured.
Gene: Protein-coding gene on chromosome 4 (139,015,772 to 139,045,939, forward strand). Ensembl gene ENSG00000151014.
Subcellular location: Cytoplasm; Nucleus; Cytoplasm, perinuclear region; Mitochondrion
Subcellular location (Human Protein Atlas): Nuclear bodies; Cytosol; Nucleoplasm
Pathways (Reactome):
Circadian clock: BMAL1:CLOCK,NPAS2 activates circadian expression
Gene Ontology:
Molecular function: NADP phosphatase activity; NADPH phosphatase activity; protein binding; 3'-5'-RNA exonuclease activity; mRNA binding; poly(A)-specific ribonuclease activity; catalytic activity; hydrolase activity, acting on ester bonds
Biological process: NADP+ metabolic process; circadian regulation of gene expression; circadian rhythm; mRNA catabolic process; mRNA stabilization; negative regulation of gene expression; negative regulation of osteoblast differentiation; positive regulation of fat cell differentiation; regulation of circadian rhythm; response to lipopolysaccharide; transcription by RNA polymerase II; regulation of embryonic development
Cellular component: cytosol; mitochondrion; nuclear body; cytoplasm; nucleoplasm; nucleus; perinuclear region of cytoplasm; P-body
Genetic constraint (gnomAD): Loss-of-function variants: 18 observed, 35.42 expected, observed/expected ratio (o/e) 0.51, 90% interval 0.35 to 0.75. The upper end of that interval is the gene's LOEUF score, 0.75, which puts it in group 3 of 6, group 1 being the genes least tolerant of losing a copy. Missense variants: 474 observed, 514.47 expected, observed/expected ratio (o/e) 0.92, 90% interval 0.85 to 0.99. Synonymous variants: 231 observed, 205.73 expected, observed/expected ratio (o/e) 1.12, 90% interval 1.01 to 1.25.
Homologues: Orthologues: chimpanzee NOCT (99% identical), rabbit NOCT (95% identical), guinea pig NOCT (93% identical), dog NOCT (92% identical), pig NOCT (92% identical), rat Noct (90% identical), macaque NOCT (86% identical), mouse Noct (80% identical), tropical clawed frog noct (72% identical), zebrafish nocta (56% identical), zebrafish noctb (55% identical), Drosophila melanogaster cu (42% identical). Paralogues in human: PDE12 (28% identical), CNOT6L (25% identical), CNOT6 (24% identical), ANGEL2 (23% identical), ANGEL1 (23% identical).
Diseases named in the same sentence as NOCT in open-access papers:
NOCT is named in the same sentence as 13 diseases in open-access papers, as found by Europe PMC text mining. Sharing a sentence is not in itself a finding about the gene and the disease. The quoted sentences say what the papers report.
Obesity (10 papers, 2009 to 2024). Accumulation of substantial excess body fat. "Nocturnin knockout was shown to protect against high-fat-diet-induced obesity and hepatic steatosis." (PMID 39061889, 2024). "Nocturnin knockout mice exhibited a resistance to diet-induced obesity, decreased triglycerides levels and improved insulin sensitivity." (PMID 23922759, 2013). "This synchronization may lead to more efficient energy utilization by adipose and, in turn, may explain the effect of clock-related genes, such as Nocturnin, on resistance to diet-induced obesity." (PMID 19203388, 2009). "Importantly, Nocturnin knockout mice were protected from diet-induced obesity." (PMID 23922759, 2013). "Nocturnin in Per2-/- knockout mice have normal circadian mechanisms, although they display resistance to HFD-induced obesity and hepatic steatosis, which indicates that Nocturnin is downstream of the core circadian clock." (PMID 31139087, 2019). "Mice lacking Nocturnin are resistant to diet-induced obesity and hepatic steatosis, linking its function to lipid metabolism." (PMID 25412178, 2014). "The expression of Nocturnin is robustly rhythmic in liver at both the mRNA and protein levels, and mice lacking Nocturnin are resistant to diet-induced obesity and hepatic steatosis." (PMID 20582318, 2010). "Mice lacking Nocturnin (Noc−/−) are resistant to diet-induced obesity and hepatic steatosis." (PMID 20582318, 2010).
lung carcinoma (2 papers, 2022 to 2024). "Next, we confirmed the significantly downregulated mRNA expression of AJUBA, WTIP, SAMD4A, and NOCT and moderately increased expression of PNRC1 in YAP/TAZ knockdown HCT116 cells by qPCR analysis; this pattern was also observed in A549 lung cancer cells and MDA-MB-231 breast cancer cells." (PMID 39046443, 2024).
diabetes (1 paper, 2016). "CCRN4L (also known as Nocturnin) is expressed in a circadian fashion and studies in mice indicate that CCRN4L activates PPAR-γ, a gene that promotes bone adipogensis as opposed to osteoblast formation and that harbors a known diabetes risk variant in humans." (PMID 26943675, 2016).
Insulin resistance (1 paper, 2019). Increased resistance towards insulin, that is, diminished effectiveness of insulin in reducing blood glucose levels. "In addition, NOCTURNIN seems to be involved in the regulation of glucose homeostasis and insulin sensitivity and may promote insulin resistance." (PMID 31467910, 2019).
steatosis (1 paper, 2022). Increased lipid within the cytoplasm of cells. "Furthermore, the expression levels of CYP1A1, NOCT, and TUBB6 were regulated, indicating the effects of improving the antioxidant capacity of liver tissues, reducing the steatosis of hepatocytes, and inhibiting the inflammatory reaction of hepatocytes, respectively." (PMID 35408620, 2022).
tumor (3 papers, 2014 to 2023). "Fitness measurements showed that NocT is required for a competitive colonization of the plant tumour by A. tumefaciens." (PMID 25299655, 2014). "In this work, we investigated the structural and biochemical properties of the PBP NocT of A. tumefaciens C58 which senses at least two opines: nopaline and pyronopaline, a lactam nopaline-derivative that can also be found in plant tumours." (PMID 25299655, 2014).
infection (1 paper, 2022). The state of being infected such as from the introduction of a foreign agent such as serum, vaccine, antigenic substance or organism. "We found that Tristetraprolin (TTP), Nocturnin (NOCT or CCR4NL), and Zinc Finger CCCH-Type Containing 12A (ZC3H12A or Regnase-1) were all up-regulated during the infection." (PMID 35573800, 2022).
metabolic disorders (1 paper, 2019). "Chronic NOCTURNIN overexpression may promote metabolic disorders through increased absorption and storage of fats in adipocytes." (PMID 31467910, 2019).
NOCT also shares sentences with these, for which no sentence is quoted: Hepatic steatosis (5 papers); breast carcinoma (1); cancer (1); neurodegenerative disease (1); squamous cell lung carcinoma (1).